HAVCR1 (hepatitis A virus cellular receptor 1)
Diseases named in the same sentence as HAVCR1 in open-access papers (continued):
Sharing a sentence is not in itself a finding about the gene and the disease.
tumor (40 papers, 2013 to 2026). "Elevated levels have been linked to poor survival outcomes, yet paradoxically, TCGA data show that higher HAVCR1 (KIM-1) mRNA expression in tumours is associated with improved overall survival." (PMID 40244290, 2025). "Highlighting an example, we identified a self-antigen DLSRRDVSL originating from tumor-specific gene HAVCR1 and present by a common allele HLA-B*08:01, covering over 15% of the U.S. population." (PMID 40672284, 2025). "Intriguingly, HAVCR1 expression significantly changed the tumor microenvironment, suggesting that HAVCR1 overexpression in tumors is associated with the invasion of non-tumor cells, such as immune cells and mesenchymal cells." (PMID 35754803, 2022). "By setting RFS as the survival outcome, we found that male patients, poorly differentiated tumor and high HAVCR1 expression were risk factors of shorter RFS." (PMID 30388143, 2018). "Additionally, to investigate the regulatory function of B cell loss in the anti-tumour responses mediated by T cells, Havcr1 deletion was performed in B cells." (PMID 37857611, 2023). "Public datasets (CPTAC, TCGA, and GEO) show that HAVCR1 expression in tumor tissue correlates with higher tumor grade and stage, highlighting the potential value of exploring the longitudinal relationship between plasma proteomics and tumor characteristics." (PMID 40928391, 2026). "A decrease in HAVCR1 levels therefore likely has a tempering effect on inflammation, with inhibition of HAVCR-mediated signalling constituting a new type of anti-tumour therapy." (PMID 40225784, 2025). "IHC analysis of preoperative biopsy samples indicated that HAVCR1 positive staining was primarily observed on the cell membrane and cytoplasm of tumor cells." (PMID 40406257, 2025). "The novel nomogram predictive model, based on preoperative clinicopathological factors such as tumor size, histological type, presence of ulcers, and HAVCR1 expression, provides valuable guidance for selecting treatment strategies for EGC patients." (PMID 40406257, 2025). "Because HAVcR-1 can bind PS, it is possible that the released HAVcR-1 ectodomain was sequestered within the tumour, binding to TIM-4 and PS, preventing the activation of infiltrating immune cells." (PMID 35204839, 2022). "It has been shown that HAVCR1 is involved in the formation, maintenance and function of tight junctions, key components of tumor metastasis." (PMID 35754803, 2022). "Taken together, HAVCR1 acts as a costimulatory molecule during tumor treatment that can enhance the antitumor effect of lymphocytes and induce tumor microenvironmental changes for effective antitumor immunity." (PMID 35754803, 2022). "We calculated the correlation between HAVCR1 and immune checkpoint molecules, known to be important for tumorigenesis or tumor treatment, and visualized them by R package “corrplot”." (PMID 35754803, 2022). "HAVcR-1 overexpression in colorectal cells resulted in no change in cell migration; however, overexpression in PC-3 showed a potential decrease in wound healing and, therefore, proposes HAVcR-1 as a tumour suppressor." (PMID 35204839, 2022). "Hepatitis A virus cellular receptor (HAVCR1) is a type-1 integral membrane glycoprotein that plays a key role in immunity and renal regeneration and is abnormally expressed in various tumor types." (PMID 35754803, 2022). "By performing univariate analysis, we found that older age, poorly differentiated tumor, advanced pathological stages (III/IV), with residual tumor and high HAVCR1 expression were risk factors of shorter OS." (PMID 30388143, 2018). "HAVCR1 overexpressed on the surface of tumor cells could also be an excellent tumor antigen to use in CAR-T cell therapy." (PMID 35754803, 2022).
tumor (continued). "Consequently, HAVCR1 can be considered as an effective biomarker that is related with tumor development and progression." (PMID 31885544, 2019). "Multivariate analysis confirmed that high HAVCR1 expression was an independent indicator of shorter OS (HR: 1.698, 95%CI: 1.221–2.361, p = 0.002), after adjustment of older age, differentiation status, pathological stages and the presence of residual tumor." (PMID 30388143, 2018). "Then, we checked HAVCR1 protein expression in some human tumor tissues." (PMID 30388143, 2018). "It is currently unclear whether HAVCR1 expression can affect tumor infiltration of immune cells." (PMID 35754803, 2022). "In clear cell renal carcinoma (RCC) cells, HAVCR1 upregulation and its shedding activate the IL-6/STAT-3/HIF-1A axis, which is a signaling pathway enhancing angiogenesis and tumor growth." (PMID 30388143, 2018). "Consistent with prior tissue analyses, we confirmed significantly higher HAVCR1 expression in tumor versus adjacent non-tumor tissues, correlating with tumor stage and grade." (PMID 40928391, 2026). "No changes in HAVCR1 expression were observed in different tumor stages, implying that HAVCR1 expression is not related to tumor staging." (PMID 35754803, 2022). "A possible explanation as to why this was not the case is that the HAVcR-1 ectodomain is sequestered within the tumour." (PMID 35204839, 2022). "HAVCR1 can also affect the MEK/ERK signaling pathway and influence tumor progression." (PMID 35754803, 2022). "Finally, analysis of The Cancer Genome Atlas (TCGA) data revealed that elevated HAVCR1 mRNA expression in the two most common types of RCC, clear cell and papillary RCC, tumours correlated with significantly improved overall patient survival." (PMID 34088927, 2021). "If this was the case, the release of the HAVcR-1 ectodomain may contribute to the nonresponsiveness of many tumour-infiltrating immune cells and would be of interest for future study." (PMID 35204839, 2022). "Ultimately, we found that ECGs presented different profiles across 20 cancer types, with CD47 and TYRO3 more frequently exhibiting copy number increases rather than losses in the majority of tumours, while AXL and HAVCR1 showed a relatively opposite trend." (PMID 40576208, 2025).
cancer (34 papers, 2017 to 2026). A tumor composed of atypical neoplastic, often pleomorphic cells that invade other tissues. "Since invasion is a hallmark of malignancy and a prerequisite for cancer metastasis, this proposes HAVcR-1 as a potential anti-metastatic target." (PMID 35204839, 2022). "Evidence currently suggests that HAVcR-1 overexpression seen in cancer is linked to TJ disruption and, therefore, links HAVcR-1 to cancer metastasis." (PMID 35204839, 2022). "HAVcR-1 has been linked to tight junctions (TJs), which have an important role in the prevention of cancer metastasis." (PMID 35204839, 2022). "Previous studies found that HAVCR1 is overexpressed in numerous cancers and its upregulation might be associated with cancer development and progression." (PMID 30388143, 2018). "In addition, we noted that the hepatitis A virus cell receptor (HAVCR1) was only highly expressed in C2, however in our previous studies we noted that HAVCR1 was also strongly associated with immune escape, and may serve as a new target for cancer immune escape." (PMID 40881682, 2025). "Studies have shown that the overexpression of HAVCR1 can lead to the disruption of tight junctions between cells, which in turn facilitates cancer cell metastasis." (PMID 40406257, 2025). "For example, we highlighted FAM83A, GJB3 and HAVCR1 as illustrative examples to demonstrate the effectiveness of denoising and validate their prognostic value using independent the cancer genome atlas program (TCGA) clinical data." (PMID 38819253, 2024). "Proteins including CXCL14, GDF15, HAVCR1, and CDCP1 were identified as predominant contributors to the risk of cancer." (PMID 38016990, 2023). "This work also demonstrated that HAVcR-1 has the capacity to alter cell behaviour to promote pro-cancer and pro-metastatic phenotypes." (PMID 35204839, 2022). "HAVcR-1 has been found to be upregulated in certain cancers, including breast, ovarian, colon and renal cancer." (PMID 35204839, 2022). "HAVcR-1 is, therefore, a molecule of interest for cancer diagnosis and a potential target for cancer therapies." (PMID 35204839, 2022). "Thus, HAVCR1 overexpression may be a diagnostic biomarker for several cancers." (PMID 31885544, 2019). "Especially, HAVCR1 overexpression promotes the development and progression of several human cancers." (PMID 31885544, 2019). "In RNA-level analyses, HAVCR1 expression was significantly elevated in tumors relative to adjacent normal tissues, as confirmed by the TCGA, GSE6344, GSE213324, and GSE53757 datasets, underscoring its strong association with cancer development." (PMID 40928391, 2026). "HAVcR-1 expression and ectodomain release in cancer is still poorly categorized." (PMID 35204839, 2022). "The overexpression of HAVcR-1 in cell lines results in decreased TJs, and HAVcR-1 overexpression in cancer is likely to also result in decreased TJs, which may mediate metastasis." (PMID 35204839, 2022). "The HAVcR-1 ectodomain is, therefore, a potential biomarker for certain cancers." (PMID 35204839, 2022). "Disagreement in the assessment of the HAVcr-1/KIM-1/TIM-1 expression in cancer tissues may be explained by different sensitivity of the immunochemical methods or unique epitope specificity of AKG7 antibody." (PMID 34603757, 2021). "Besides the specific upregulation in several human cancers, the monoclonal antibody binds to HAVCR1 can be internalized into the cells, making it an attractive target for antibody-mediated therapy, such as antibody-drug conjugates (ADCs) in certain cancers." (PMID 30388143, 2018). "Specifically, NEFH, hepatitis A virus cellular receptor 1 (HAVCR1, 5q33.2), interferon, alpha-inducible protein 27 (IFI27, 14q32), PCSK5, and the arylsulfatase D gene (ARSD, Xp22.3) have been implicated in a variety of cancers." (PMID 28249600, 2017). "Nonetheless, the function of HAVCR1 in pan-cancer remains unknown." (PMID 35754803, 2022).
cancer (continued). "Subsequently, we analysed the expression levels of these genes across 33 types of cancer and found that AXL, MERTK, TYRO3, CD24, HAVCR2 and CD47 exhibited higher expression levels, while TIMD4 and HAVCR1 showed relatively lower expression." (PMID 40576208, 2025). "Furthermore, there is a lack of study into the release of the HAVcR-1 ectodomain into the circulation and the use of this as a potential biomarker for use in blood tests for cancer diagnosis and monitoring." (PMID 35204839, 2022). "The overexpression of HAVcR-1 appeared to affect changes in the phosphorylation status of α and β-catenins, both of which are involved in cell motility and are part of the complex involved in HGF signalling, a key factor in the metastatic behaviour of cancer cells." (PMID 35204839, 2022).
infection (21 papers, 2009 to 2025). The state of being infected such as from the introduction of a foreign agent such as serum, vaccine, antigenic substance or organism. "Taken together, the current data on the association between susceptibility to infection and polymorphisms in HAVCR1 exon 4 suggest that short-HAVCR1 plays a protective role and explain the high evolutionary pressure on HAVCR1 exon 4 towards shorter variants." (PMID 39595207, 2024). "This was accompanied by an increase in tubular injury markers, such as Havcr1, Col1a1 and Col1a2 which encode KIM-1 and type 1 and 2 collagen, respectively; markers that were also identified in our study with PbA infection." (PMID 40661967, 2025). "However, in HIV-infected cells, HAVCR1 has the opposite effect blocking the release of viral particles and reducing infection of naive cells." (PMID 39595207, 2024). "HAV is transmitted through the fecal-oral route, so the ability of HAV to interact with HAVCR1 in a wide pH range suggested that HAVCR1 could mediate infection of cells in the gastrointestinal track." (PMID 19860892, 2009). "Our studies showed that the alteration of HAV by soluble HAVCR1 is a Ca-dependent process, which is consistent with previously published reports showing that binding of HAV to cells and infection is enhanced by Ca ions." (PMID 19860892, 2009). "We show here that TIM1 (HAVCR1) is not an essential cellular receptor for HAV entry into cultured cells or required for viral replication and pathogenesis in permissive strains of mice, although it may facilitate early stages of infection by binding phosphatidylserine on the eHAV surface." (PMID 28874468, 2017).
infectious disease (2 papers, 2011 to 2024). A disorder directly resulting from the presence and activity of a microbial, viral, or parasitic agent in humans. "Our work focused on understanding the molecular basis for the differential function of human HAVCR1 exon 4 ins/del polymorphisms, which have been associated with immune and infectious diseases." (PMID 39595207, 2024). "Polymorphisms in HAVCR1 exon 4 have been associated with susceptibility to infectious diseases." (PMID 39595207, 2024). "Although the association between HAVCR1 exon 4 variants with immune and infectious diseases has been well established, the molecular basis for the differential function of the HAVCR1 variants has not been explored." (PMID 39595207, 2024).
HAVCR1 also shares sentences with these, for which no sentence is quoted: diabetes (83 papers); diabetic nephropathy (57); renal fibrosis (54); injury (39); renal failure (33); Hypertension (26); heart failure (21); Hyperglycemia (20); renal dysfunction (20); acute tubular necrosis (15); Cirrhosis (14); type 1 diabetes (14); cardiovascular disease (12); end-stage renal disease (12); fibrosis (12); nephritis (12); glomerulonephritis (10); lupus nephritis (10); chronic heart failure (9); hepatorenal syndrome (8); hydronephrosis (8); cyst (7); endothelial dysfunction (7); glomerular disease (6); hyperuricemia (6); Insulin resistance (6); pyelonephritis (6); hyperlipidemia (5); Hyperoxaluria (5); ischemia reperfusion injury (5).
A further 145 diseases each share a sentence with HAVCR1 in 5 papers or fewer.